MACC1 (MET transcriptional regulator MACC1)
Diseases named in the same sentence as MACC1 in open-access papers (continued):
Sharing a sentence is not in itself a finding about the gene and the disease.
colon carcinoma (continued). "In addition, miR-338-3p modulates the growth, apoptotic and migration ability of colon cancer cell through regulating MACC1." (PMID 32976115, 2020). "Only the genotype AG in MACC1 SNP rs975263 could be identified to be correlated with a decreased survival, but restricted in young colon cancer patients in early stage 18." (PMID 32174779, 2020). "Metastasis-associated in colon cancer 1 (MACC1) was first identified in colon tumors by differential display RT-PCR, and was shown to be involved in the regulation of colon tumor growth and metastasis through the hepatocyte growth factor (HGF)/c-Met signaling pathway." (PMID 33425885, 2020). "Similarly, worse survival and 5-year SR were also observed for the patients with MACC1 above the cut-off in either colon cancer (71.9 vs. 94.4 months; p < 0.001) or rectal cancers (43.8 vs. 75.0 months; p < 0.001)." (PMID 30805302, 2019). "miR-23b-3p has not been widely related with cancer, nor with colon cancer, although it has been predicted to be a regulator of MACC1 protein (metastasis-associated in colon cancer 1)." (PMID 30862091, 2019). "MACC1 expression was increased in colonosphere cells compared to adherent colon cancer cells, and DBC1 overexpression further increased MACC1 expression in colonospheres and promoted sphere-forming abilities of colon cancer cells and drug resistance of colonospheres." (PMID 30082743, 2018). "In addition to stimulating colon cancer cell proliferation and metastasis, MACC1 promotes chemoresistance and CSC-like properties in colon cancer cells." (PMID 30082743, 2018). "Given our recent report that DBC1 is a critical regulator of Wnt/β-catenin signaling in CRC9, we next tested the possibility that DBC1 may also contribute to β-catenin-mediated upregulation of MACC1 in colon cancer cells." (PMID 30082743, 2018). "In addition, two genes that either suppress (SASH1) or induce (MACC1) metastasis in colon cancer were included." (PMID 30340556, 2018). "Activation of Wnt signaling stimulated MACC1 expression in colon cancer cells." (PMID 30082743, 2018). "Here, we showed MACC1 as a direct target of the canonical Wnt signaling in colon cancer cells." (PMID 30082743, 2018). "The colon cancer 1 (MACC1) gene is an essential pro-metastatic factor in human colon cancer." (PMID 29158523, 2017). "MACC1 was also an independent prognostic factor for colon cancer." (PMID 27793161, 2016). "Metastasis-associated in colon cancer-1 (MACC1) was first identified to be overexpressed in primary and metastatic tumor specimens of colon cancer as compared to normal colon mucosa and was found to be indicative of metastasis as well as poor survival of the patients." (PMID 23497677, 2013). "Furthermore, MACC1 has been found to stimulate proliferation, motility and invasion in colon cancer cells through transcriptionally upregulating c-MET." (PMID 23497677, 2013). "MACC1 is a recently identified molecule involved in metastasis of colon cancers." (PMID 23414367, 2013). "Colon cancer patients characteristics and circulating MACC1 transcript levels in plasma." (PMID 23166620, 2012). "Low MACC1 indicates longer distant metastasis-free survival (MFS) for colon cancer patients." (PMID 21955323, 2011). "Notably, in vivo MACC1 was also enriched in tumor buds and cells at the invasive front of colon carcinoma, making it tempting to speculate about the role of MACC1 in leader cell determination during collective invasion." (PMID 37051546, 2023). "First, the SP1 motif is necessary for MACC1-mediated MET expression in colon cancer cells, which suggests that MACC1 regulation of MET requires involvement with SP1; in terms of this, MACC1 may not interact with SP1 and therefore does not regulate pancreatic cancer metastasis via the MET pathway." (PMID 36333284, 2022).
colon carcinoma (continued). "Although MACC1 was shown to be a critical regulator and biomarker for progression and metastasis in over 20 types of cancer, including colon cancer, HCC, bladder cancer, and esophageal cancers, the mechanisms by which MACC1 is involved in the development and progression of COAD remain unclear." (PMID 36545127, 2022). "Moreover, MACC1 depletion was demonstrated to inhibit the PI3K/AKT axis in colon cancer cells." (PMID 34939526, 2022). "Therefore, a downregulation of miR-143 could enhance colon cancer metastasis through a mechanism of MACC1-induced HGF-MET signaling pathway." (PMID 26064956, 2015). "In vivo, MACC1 impacts tumor initiation and progression as well as liver and lung metastases in colon cancer xenografted (CDX, PDX) and MACC1 transgenic mouse models." (PMID 39580452, 2024). "Early studies identified MACC1 as a key regulator of HGF-MET signaling, and MACC1 mRNA levels have been found to predict colon cancer metastasis." (PMID 37381723, 2023). "MACC1′s involvement in the AKT signaling pathway has also been found in nasopharyngeal carcinoma, colon cancer, pancreatic cancer, and human glioblastoma." (PMID 36979146, 2023). "The exploration of the MACC1/HGF/c-MET pathway in colon cancer provides favorable evidence for drug targeting of MACC1 and regulation of MACC1/HGF/c-MET in colon cancer therapy." (PMID 35874635, 2022). "Specifically, inhibition of the MACC1/HGF/c-MET axis contributes to the treatment and prognosis of colon cancer and also helps to suppress the proliferation and invasion of colon cancer cells." (PMID 35874635, 2022). "According to the results of in vitro experiments, the recession of MACC1 and c-MET in colon cancer cells can indeed regulate the proliferation and migration of cancer cells." (PMID 35874635, 2022). "Meanwhile, the expression of c-MET in colon cancer cells varied with the change of MACC1 and showed positivity for colon cancer, and c-MET promoted the development and progression of colon cancer." (PMID 35874635, 2022). "This experiment showed that there was also an upstream-downstream relationship between MACC1 and c-MET in colon cancer cells and tissues, both of which formed the MACC1/HGF/c-MET axis." (PMID 35874635, 2022). "MACC1, a critical modulator of the HGF/MET signaling pathway, was revealed to predict colon cancer metastasis." (PMID 34939526, 2022). "The results indicated that MACC1 knockout inhibited the ability of proliferation and EMT of colon cancer cells (P < 0.01)." (PMID 35874635, 2022). "However, it remains unknown how the expression of MACC1 is regulated in colon cancer cells." (PMID 30082743, 2018). "MACC1 functions as a key activator of the HGF/c-MET signaling pathway, promoting colon cancer cell proliferation, invasion and metastasis in culture, and the growth and metastasis of tumors in xenograft models." (PMID 25009663, 2014). "Overexpression of MACC1 induces down-stream activation of HGF/c-Met and promotes metastasis of colon cancer, while silencing of MACC1 leads to reduced tumor proliferation, decreased cell migration, and a lack of new metastasis." (PMID 23414367, 2013). "MACC1 enhances proliferation and invasion as well as HGF-induced scattering of colon cancer cells in vitro and promotes tumor growth and metastasis of xenografted tumors in mouse." (PMID 23717574, 2013). "MACC1 is directly phosphorylated by MEK1, a component of the Erk mitogen-activated protein kinase (MAPK) pathway, resulting in enhanced Erk activation as well as migration and metastasis in colon cancer cells." (PMID 38396744, 2024). "MACC1 is a key regulator of the hepatocyte growth factor (HGF) receptor and has mainly been identified as an independent prognostic factor for metastasis formation and metastasis-free survival in colon cancer." (PMID 37304008, 2022).
colon carcinoma (continued). "It is interesting to note that MACC1 expression is positively correlated with β-catenin expression in CRC tissues and that MACC1 overexpression in colon cancer cells promotes migration, invasion, and tumor formation through stimulating β-catenin and its target gene expression." (PMID 30082743, 2018). "Given that MACC1 has been shown to induce CSC-like characteristics including self-renewal capability and drug resistance, we next investigated the role of DBC1 in the regulation of MACC1 expression in colonospheres and in CSC-like properties of colon cancer cells." (PMID 30082743, 2018). "In addition, DBC1 depletion greatly reduced LiCl-induced expression of MACC1, indicating that DBC1 is required for Wnt/β-catenin-mediated expression of MACC1 in colon cancer cells." (PMID 30082743, 2018). "Our findings imply that, in addition to stimulating Wnt/β-catenin-mediated MACC1 expression, DBC1 may also contribute to a more aggressive phenotype of colon cancer by promoting MACC1-mediated transcription in colon cancer cells." (PMID 30082743, 2018). "Expression levels of MACC1 in colon cancer without distant metastases were significantly higher in primary tumors that later developed distant metastases, compared to those that did not metastasize within a 10-year follow-up period." (PMID 26884752, 2016). "Previous studies have shown that MACC1 acts as a transcription activator for c-MET and as a key regulator of HGF-c-MET signaling pathway in colon cancer, promoting proliferation, invasion and HGF-induced scattering of colon cancer cells and xenograft growth and metastasis in vivo." (PMID 23497677, 2013). "Recently, MACC1 has been identified as a prognosis biomarker for colon cancer, which promotes proliferation, invasion and hepatocyte growth factor (HGF)-induced scattering of colon cancer cells in vitro and in vivo." (PMID 21923915, 2011). "Given the tight correlation between MACC1 and c-MET in colon cancer, we also examined the expression level of c-MET mRNA to determine whether such correlation exists in HCC." (PMID 21955323, 2011). "MACC1 may act as a key regulator of the HGF/c-MET pathway, leading to distant metastases in colon cancer." (PMID 21955323, 2011). "In colon cancer cells, MAPK signaling could be hyperactive by transfection of MACC1, and HGF-induced cell scattering mediated by MACC1 could be abrogated by MEK specific inhibitors, whereas not by PI3K specific inhibitors." (PMID 21923915, 2011). "Because MACC1 may promote cell migration and invasion by upregulating the downstream c-MET gene in colon cancer, we sought to determine whether such a mechanism might contribute to the increased invasiveness of HCC induced by MACC1." (PMID 21955323, 2011). "Here we report that MACC1 is a direct target of Wnt/β-catenin signaling pathway in colon cancer cells and that DBC1 functions as a coactivator for Wnt-mediated MACC1 expression by promoting the activity of a LEF1/β-catenin-dependent enhancer located in intron 1 of MACC1 gene." (PMID 30082743, 2018). "Thus, MACC1 represents an early prognostic indicator for colon cancer metastases that is independent of age, sex, tumor infiltration, nodal status, and lymph vessel invasion." (PMID 26884752, 2016). "It is not difficult to find a close relationship between MACC1 and c-MET as well as HGF in colon cancer by extracting data from StarBase Pan-cancer." (PMID 35874635, 2022). "In contrast to MACC1, SH3BP4 did neither induce cell migration nor invasion in colon cancer cells." (PMID 38144523, 2023).
gastric cancer (52 papers, 2011 to 2025). A primary or metastatic malignant neoplasm involving the stomach. "Mechanistically, AFP facilitates the migration and invasion of gastric cancer cells, potentially by upregulating the expression of metastasis-associated in colon cancer 1 (MACC1)." (PMID 40430002, 2025). "For instance, ORAI1 has been shown to enhance gastric cancer cell migration and invasion by targeting MACC1 (metastasis-associated in colon cancer protein 1)." (PMID 38672434, 2024). "For example, Metastasis associated in colon cancer 1 (MACC1) is significantly upregulated to facilitate the Warburg effect and ensure gastric cancer growth in glucose deprivation‐induced metabolic stress." (PMID 37860928, 2023). "From a molecular point of view, depressive symptom severity was significantly higher in gastric cancer patients having higher plasma levels of catecholamines, elevated metastasis-associated in colon cancer-1 (MACC1) oncogene levels and metastasis." (PMID 37987329, 2023). "MACC1 overexpression has also been linked with unfavorable prognosis in different tumors, such as lung cancer, gastric cancer, ovarian cancer, endometrial cancer, cervical cancer, osteosarcoma, and renal cell carcinoma." (PMID 34577857, 2021). "An earlier study indicated that MACC1 was upregulated in gastric cancer (GC) causing elevated cell glycolysis under metabolic stress induced by nutrient deprivation during tumor progression." (PMID 33751856, 2021). "We previously reported that metastasis-associated in colon cancer-1 (MACC1) contributed to the vasculogenic mimicry (VM) formation in human gastric cancer (GC)." (PMID 27280289, 2016). "Yet, two studies in gastric cancer associated MACC1 with higher fibronectin expression." (PMID 37051546, 2023). "Also, high MACC1 protein expression was significantly associated with liver metastasis of gastric cancer." (PMID 24325214, 2013). "Further, subsequent studies have shown that overexpression of MACC1 is associated with poor disease-free survival in patients with gastric carcinoma and lung adenocarcinoma, respectively, and it was found that MACC1 is more frequently expressed in vascular invasive hepatocellular carcinoma." (PMID 22251819, 2012). "In this context, higher levels of circulating MACC1 mRNA, peripheral soluble or tumor lesion protein expression was significantly associated with poor survival in patients such as lung cancer, gastric cancer, glioma, cervical cancer, hepatocellular, and renal pelvis carcinoma." (PMID 30805302, 2019). "Upon glucose deprivation, gastric cancer cells showed increased formation of stress fibers, caused by DLC3 downregulation and subsequent MACC1 upregulation." (PMID 37051546, 2023). "In gastric cancer, MACC1 significantly increases the expression of TWIST1 and induces the tubular formation of human umbilical vein endothelial cells (HUVECs)." (PMID 36979146, 2023). "In line with this, in non-small cell lung and gastric cancer, MACC1 correlated with a lower expression of collagen I and fibronectin." (PMID 37051546, 2023). "In line with this, MACC1 expression resulted in increased glucose uptake, ATP levels, and lactate production in gastric cancer cells." (PMID 37051546, 2023). "MACC1 upregulates VEGF-C/VEGF-D secretion to promote human gastric cancer lymphatic angiogenesis through c-Met signaling." (PMID 36979146, 2023). "We were able to show the high effectivity of selumetinib in MACC1-expressing tumor cells and gastric cancer cells in vitro and in vivo." (PMID 35406545, 2022). "For example, High expression of MACC1 in liver cancer, gastric cancer, cervical cancer, breast cancer, non-small-cell lung cancer, and so on are related to proliferation, migration, and prognosis." (PMID 35874635, 2022). "Beside these studies on tumor tissue, in 2015 our research group published an analysis of the levels of circulating MACC1 transcripts in the plasma of a small Caucasian gastric cancer patients cohort." (PMID 35406545, 2022).
gastric cancer (continued). "It seems likely that MACC1 and S100A4 also cooperate in other cancer entities, as the two biomarkers were described for improved prognosis of ovarian or gastric cancer, which underlines its considerable cross-entity potential." (PMID 36008464, 2022). "This study shows a strong correlation of MACC1 expression with poor overall survival in a large Caucasian gastric cancer and esophageal adenocarcinoma cohort." (PMID 35406545, 2022). "[A meta-analysis from 2019 showed, in a total number of 2103 gastric cancer patients, a significant correlation of MACC1 expression levels in tumor tissue with distant metastasis and vascular invasion in gastric cancer patients." (PMID 35406545, 2022). "Further, miR-338-3p regulates EMT formation by targeting ZEB2 and MACC1/Met/Akt pathways in gastric cancer." (PMID 34429400, 2021). "MACC1 is linked to increased PI3K/Akt signaling and pharmacological Akt inhibition leads to reduced MACC1 expression in gastric cancer." (PMID 33652667, 2021). "In hepatocellular carcinoma and in gastric cancer MACC1 expression positively correlates with expression of 6-phosphofructo-2-kinase/fructose-2,6-bisphosphatase (PFKFB2) and of fatty acid synthase (FASN)." (PMID 33652667, 2021). "The same holds true when comparing MACC1 levels in plasma from gastric cancer patients compared to healthy controls." (PMID 30927479, 2019). "They identified that gastric cancer cells in the presence of MSCs led to an enhancement of FAO-associated enzymes and an increase in lncRNA-metastasis-associated in colon cancer-1 (MACC1) to promote chemoresistance and stemness." (PMID 35582574, 2019). "MACC1 subsequently binds to miR-145-5p which then enhances carnitine palmitoyltransferase 1 to induce chemoresistance and stemness behavior in gastric cancer cells." (PMID 35582574, 2019). "We showed that (a) MACC1 mRNA transcripts are detectable in plasma of patients with CRC or gastric cancer, (b) they are significantly elevated compared to healthy controls, and that (c) high levels of circulating MACC1 transcripts indicate poor survival." (PMID 30927479, 2019). "Here, we aimed to assess the relationship between metastasis associated in colon cancer‐1 (MACC1) and PDL1 and examine their effects on gastric cancer (GC) tumor immunity." (PMID 31557409, 2019). "XIST is associated with tumor progression through targeting miR-34a-5p or miR-497/MACC1 axis in nasopharyngeal carcinoma and gastric cancer individually." (PMID 29568404, 2018). "MiR-338-3p suppresses epithelial-mesenchymal transition in gastric cancer cells by targeting MACC1/Met/Akt pathway." (PMID 28348518, 2017). "To determine in general the functional role of miR-218 for the post-transcriptional regulation of MACC1, we have used an additional cancer entity of the gastrointestinal tract, employing the gastric cancer cell line MKN-45." (PMID 27462788, 2016). "Metastasis-associated in colon cancer-1 (MACC1) is an oncogene that is overexpressed in gastric cancer (GC) and plays an important role in GC progression, though it is unclear how MACC1 activity is regulated in GC." (PMID 26919111, 2016). "Consistent with our results performed with CRC cell lines, MACC1 is also a target of miR-218 in gastric cancer cells." (PMID 27462788, 2016). "Circulating MACC1 transcripts have also been used as biomarker in the context of non-small cell lung cancer and gastric cancer." (PMID 27439755, 2016). "In prospective studies we demonstrated significant correlations of circulating MACC1 transcripts in colon, rectal and gastric cancer patients’ plasma with patients’ survival." (PMID 27439755, 2016). "Currently, MACC1 expression has been further proven to contribute to unfavorable clinical outcome of patients with gastric cancer, esophageal cancer, and hepatocellular carcinoma." (PMID 26090393, 2015).